EML4 (EMAP like 4)
Diseases named in the same sentence as EML4 in open-access papers (continued):
Sharing a sentence is not in itself a finding about the gene and the disease.
non-small cell lung carcinoma (continued). "The major trials that lead to the approval of crizotinib for the treatment of EML4-ALK positive non-small cell lung cancer patients employed genetic testing by FISH to identify responders." (PMID 27863497, 2016). "For example, bioinformatics approaches led to the discovery of the TMPRSS2-ETS gene fusion in prostate cancer and the EML4-ALK fusion in non-small-cell lung cancer." (PMID 27105842, 2016). "Inhibition of the oncogenic fusion-gene EML4-ALK is a current first-line approach for patients with stage IV non-small cell lung cancer." (PMID 27863497, 2016). "Te fusion between echinoderm microtubule-associated protein 4 (EML4) and anaplastic lymphatic tumor kinase (ALK) rearrangement is present in approximately 5% of non-small cell lung cancer (NSCLC) patients." (PMID 26805736, 2016). "The EML4-ALK fusion gene is a newly discovered driver gene of non-small cell lung cancer and exhibits special clinical and pathological features." (PMID 27666544, 2016). "The transforming EML4-ALK fusion transcript was initially detected in approximately 7% of patients with non-small-cell lung cancer (NSCLC), with the fusion being mutually exclusive with the better-known EGFR mutations." (PMID 27105842, 2016). "The expression of the echinoderm microtubule-associated protein-like 4 (EML4)-ALK fusion oncogene, which is caused by a small inversion within chromosome 2p, was found in non-small cell lung cancer (NSCLC)." (PMID 27144340, 2016). "EML4 is currently under intense investigation in non small cell lung cancer where it is frequently found fused to the ALK gene." (PMID 25993117, 2015). "The authors reported the successful induction of the Eml4-Alk gene rearrangement found recurrently in non-small-cell lung cancers." (PMID 26389881, 2015). "A novel fusion gene of echinoderm microtubule-associated protein-like 4 (EML4) and anaplastic lymphoma kinase (ALK) has been recently identified in non-small-cell lung cancers (NSCLCs)." (PMID 25706305, 2015). "The EML4-ALK fusion gene was recently identified in a subset of non-small cell lung cancers (NSCLCs)." (PMID 24842630, 2014). "EML4-ALK is a fusion-type protein tyrosine kinase that is present in ∼5% of cases of non-small-cell lung cancer (NSCLC)." (PMID 24403104, 2014). "The fusion of echinoderm microtubule-associated protein-like 4 (EML4) and ALK gene by rearrangement in non-small cell lung cancer was identified and developed as a target of the ALK tyrosine kinase inhibitor, crizotinib." (PMID 24885886, 2014). "The Echinoderm microtubule-associated protein-like 4 and the anaplastic lymphoma kinase (EML4-ALK) fusion genes were discovered in non-small cell lung cancer (NSCLC) in 2007." (PMID 24992725, 2014). "For example, approximately 4% of non-small-cell lung cancers express the EML4-ALK fusion protein, providing a marker for responsiveness to the ALK kinase inhibitor crizotinib." (PMID 25594012, 2014). "The frequencies of EML4-ALK fusion gene in non-small cell lung cancer (NSCLC) with different clinicopathologic features described by previous studies are inconsistent." (PMID 25360721, 2014). "Fusion genes are often oncogenes, such as BCR:ABL in chronic myeloid leukaemia (CML), TMPRSS2:ERG in prostate cancer, EML4:ALK in non-small-cell lung cancer (NSCLC) and so on." (PMID 24564548, 2013). "Current therapeutic development is focused on targeting molecular mechanisms, and this has resulted in significant improvements in outcome for several cancer types (for example, crizotinib for EML4-ALK fusion-positive non-small cell lung cancer (NSCLC))." (PMID 24004612, 2013). "While less common than in haematological malignancies and sarcomas, recurrent gene fusions have been identified in other solid tumours, such as TMPRSS2–ERG in prostate 38 and EML4–ALK in non-small cell lung cancers." (PMID 22514011, 2012).
non-small cell lung carcinoma (continued). "Similarly, in surgically resected non-small cell lung cancer specimens, the EML4-ALK fusion protein was observed to upregulate PD-L1 expression." (PMID 41458607, 2025). "However, mutations involving the EML4-ALK fusion gene, which is typically associated with non-small cell lung cancer (NSCLC), are exceedingly rare in SCLC." (PMID 40136367, 2025). "Notably, all three cases with detailed genetic findings involved the EML4::ALK (V3) fusion type, which has been reported to be associated with poor prognosis of ALK-rearranged non-small cell lung cancer." (PMID 40224190, 2025). "Likewise, activation of NEK9 (and NEK7) promoted the activation of oncogenic EML4–ALKv3 and V5 fusion proteins that are involved in the progression of certain cancers, including non-small cell lung cancer (NSCLC) and gastric cancer." (PMID 41154634, 2025). "In this report, we describe a male non-smoker diagnosed with SMARCA4-deficient, EML4-ALK non-small cell lung cancer who has been undergoing ensartinib targeted therapy for 3 months, resulting in a significant partial response." (PMID 40416876, 2025). "For example, the identification of EML4 > ALK gene fusions in non-small cell lung cancer paved the way for the development of ALK inhibitors and recently drugs targeting tumors of any cancer type with gene fusions involving NTRK genes have been approved by the FDA43,44." (PMID 37400526, 2023). "The EML4-ALK fusion was found in 10 AYAs with non-small cell lung cancer." (PMID 36433963, 2022). "In 1208 patients with non-small cell lung cancer with tissue samples, the positive rate of EML4-ALK was 4.88% (59/1208), as determined by next-generation sequencing, the mutation rate of adenocarcinoma was 5.84% (58/994), and the mutation rate of squamous cell carcinoma was 0.47% (1/214)." (PMID 32047559, 2020). "In blood samples from 297 patients with non-small cell lung cancer, the positive rate of EML4-ALK detected by next-generation sequencing was 3.70% (11/297), the mutation rate of adenocarcinoma was 3.82% (10/262), and the mutation rate of squamous cell carcinoma was 2.86% (1/35)." (PMID 32047559, 2020). "Crizotinib, a TKI for which we have shown promising in vitro results for the treatment of GC presenting MET amplification/overactivation, is already in clinical setting for the treatment of EML4-ALK–translocated (ALK-positive) non-small cell lung cancer (NSCLC) patients." (PMID 31979110, 2020). "The positive rate of EML4-ALK was 8.52% (34/399) in 399 patients with non-small cell lung cancer, as detected by reverse transcription polymerase chain reaction; the mutation rate of adenocarcinoma was 11.62% (33/284), and the mutation rate of squamous cell carcinoma was 0.86% (1/115)." (PMID 32047559, 2020). "Notably, the ALK small molecule inhibitors have been more evaluated in ALK+ solid tumors such as EML4-ALK+ non-small cell lung cancer." (PMID 31340850, 2019). "Non-small cell lung cancer (NSCLC) is a common and rapidly fatal cancer for which targeted therapies have been markedly effective in about 20% of patients, specifically those with EGFR mutations, ROS1 rearrangements, or EML4-ALK translocations." (PMID 26623721, 2016). "Most information currently available on the clinical efficacy and causes of relapse on crizotinib treatment are collected in the context of EML4-ALK-positive non-small-cell lung cancer, which is the most common ALK-related disease, whereas little is known about other ALK-positive malignancies." (PMID 25727400, 2015). "EML4-ALK fusion gene was initially identified in 2007 in non-small cell lung cancer (NSCLC)." (PMID 25888090, 2015). "EML4-ALK is a new driver gene of non-small cell lung cancer and a target of crizotinib." (PMID 24992725, 2014).
non-small cell lung carcinoma (continued). "The discovery of the fusion gene echinodermmicro tubule associated proteinlike 4-anaplastic lymphoma kinase, EML4-ALK, in patients with non-small-cell lung cancer has led to the remarkable development of anaplastic lymphoma kinase inhibitors, such as crizotinib." (PMID 24885608, 2014). "EML4-ALK-rearranged adenocarcinoma represents about 5-7% of Non Small Cell Lung Cancer (NSCLC)." (PMID 25178493, 2014). "A number of molecular aberrations have been identified in non small cell lung cancer (NSCLC), including EGFR, BRAF, HER2 mutations, EML4-ALK, ROS1 and RET rearrangements in adenocarcinoma; FGFR mutations/amplifications, DDR2 or PIK3CA mutations in squamous cell carcinoma." (PMID 24898067, 2014). "EML4-ALK fusion gene is found in only a small subset (2–6%) of non-small cell lung cancer." (PMID 23936355, 2013). "EML4-ALK fusion gene is identified in approximately 3-13% of non-small cell lung cancer (NSCLC)." (PMID 21504625, 2011). "Similar to the discovery of NPM1-ALK in ALCL, the echinoderm microtubule-associated protein-like 4 (EML4)-ALK fusion gene was discovered as a cancer driver gene, which is detected in ~7% of patients with non-small cell lung carcinoma (NSCLC)." (PMID 37894456, 2023). "It is unclear whether surgical resection of primary pulmonary lesions, systemic antitumor therapy, targeted therapy, or localized ocular therapy are effective in treating choroidal metastases in EML4-ALK rearranged oligometastatic non-small cell lung cancer (NSCLC)." (PMID 35433411, 2022). "An ex vivo functional screen of cDNA from a non-small cell lung carcinoma (NSCLC) led to identification of EML4-ALK as a recurrent gene fusion in ∼5% of NSCLCs." (PMID 21949640, 2011). "Among these, EML4-ALK is the most common and extensively studied fusion in non-small cell lung cancer (NSCLC)." (PMID 40054123, 2025). "ALK rearrangements, including EML4-ALK fusions, are involved in subsets of non-small cell lung cancer (NSCLC) and anaplastic large cell lymphoma (ALCL)." (PMID 40547482, 2025). "For example, EML4-ALK is generated by inversion, serving as one of the driver genes in non-small cell lung cancer." (PMID 40395612, 2024). "Another circular RNA, F-circEA-2a, derived from the EML4-ALK fusion gene, has also been shown to promote cell migration and invasion in non-small cell lung cancer." (PMID 36613512, 2022). "The anaplastic lymphoma kinase (ALK) gene translocation is noted in 4–7% of non-small cell lung cancer (NSCLC) cases and results in a fusion between ALK and a second gene (most commonly EML4)." (PMID 35008185, 2021). "In conclusion, our data suggest that aberrant expression of EML4-ALK leads to the activation of the JAK2-STAT signaling pathway, which is essential for the development of non-small cell lung cancer." (PMID 34090412, 2021). "In a pancreatic cancer cell line, we found a fusion between EML4 and ALK, as known from non-small-cell lung cancer." (PMID 33441414, 2021). "Our data suggest that the aberrant expression of EML4-ALK leads to JAK2-STAT signaling pathway activation, which is essential for the development of non-small cell lung cancer." (PMID 34090412, 2021). "In particular, the discovery of EML4-ALK has led to accelerated approval of several ALK inhibitors by the U.S. Food and Drug Administration (FDA) for the treatment of non-small cell lung cancer with stunning clinical responses." (PMID 32771039, 2020). "Expression of the Eml4–Alk fusion gene in this model results in pathological and molecular characteristics of typical ALK + human non-small cell lung cancers (NSCLC)." (PMID 30079312, 2018). "Human non-small cell lung cancer (NSCLC) cell lines harboring wild-type ALK (A549), EML4-ALK translocation (H3122) and murine Lewis Lung Cancer (LLC) cells were investigated." (PMID 29304828, 2018).
non-small cell lung carcinoma (continued). "The resulting cells invariably harbor the Eml4–Alk inversion, express the Eml4–Alk fusion gene, display histopathological and molecular features typical of ALK1 human non-small cell lung cancers (NSCLCs), and respond to treatment with ALK inhibitors." (PMID 28677007, 2017). "In non-small cell lung cancer (NSCLC), EML4-ALK fusion is present in approximately 3–7% of cancers, and these patients are eligible for targeted treatment with crizotinib and ceritinib." (PMID 26980749, 2016). "In both studies, two to three months after inoculation, all mice developed lung tumors expressing the Eml4-Alk fusion oncogene and displaying histopathological and molecular features typical of ALK-positive human non-small-cell lung cancer." (PMID 26389881, 2015). "There are currently no molecular targeted approaches to treat SCLC similar to those used successfully against non-small-cell lung cancer (NSCLC), such as erlotinib targeting of mutant EGFR or crizotinib targeting of EML4-ALK fusion proteins." (PMID 25198282, 2014). "In non-small cell lung carcinoma (NSCLC), the most common ALK rearrangement is a fusion of ALK gene and echinoderm microtubule-associated protein-like 4 (EML4) gene, formed as a result of a small inversion within the short arm of chromosome 2, where the genes are located." (PMID 23484153, 2013). "Recently the fusion gene, EML4-ALK, resulting from an inversion at 2p21/2p23, was found in 3–7% of non-small cell lung cancer (NSCLC)." (PMID 19337251, 2009). "EML4-ALK represents an interesting variation on this theme, because it is a special fusion protein that occurs in non-small-cell lung cancer, i.e. a solid tumor, where disorder appears to play a double role in pathological activation of the protein." (PMID 19888473, 2009). "In non-small cell lung cancer (NSCLC), ALK fusion proteins, exemplified by EML4-ALK, promote tumor cell proliferation, survival, and migration through persistent activation of downstream oncogenic signaling pathways, representing a key molecular subtype and a primary target for precision therapy." (PMID 41614760, 2025). "For instance, the oncogenic EML4–ALK fusion, resulting from the inversion of chromosome 2, on which both genes are located, was described in anaplastic lymphoma, and later in patients with non-small cell lung cancer." (PMID 38292185, 2024). "In non-small-cell lung cancer cells with emL4-ALK gene fusion, inhibition of SMYD2 expression or protein catalytic function leads to decreased levels of methylation and phosphorylation of EML4-AlK protein K1610, which inhibits cell growth." (PMID 35432530, 2022). "EML4-ALK fusion is most often detected in a subset of non-small cell lung carcinoma in never smokers and has unique pathologic features." (PMID 35328664, 2022). "Subsequently, other gene fusion partners to ALK were identified; EML4 is the most common of these, and ALK-rearrangements are found in 4–7% of non-small cell lung cancer (NSCLC) patients, mostly in younger patients with light or nonsmoking history and adenocarcinoma histology." (PMID 32640547, 2020). "Other frequently recurring fused kinases are ALK (found in 18 cell lines) and ROS1 (in 6 cell lines), both well known as cancer drivers in lung adenocarcinoma (EML4-ALK fusion) and non-small cell lung cancer (ROS1 rearrangements), for which different inhibitor drugs have been developed." (PMID 33257674, 2020). "Around 8–10% of sporadic NB tumours present with point mutations in the kinase domain of the full-length ALK receptor; this is in contrast to the oncogenic NPM-ALK and EML4-ALK fusions that drive ALK-positive anaplastic large cell lymphoma (ALCL) and non-small cell lung cancer (NSCLC), respectively." (PMID 31088252, 2019).
non-small cell lung carcinoma (continued). "Furthermore, one of the non-small cell lung cancer fusion gene, EML4-ALK, which activates ALK kinase and contributes to poor prognosis, derives from the circRNA-circ F-EA, which can be detected in the plasma of patients who harbored the EML4-ALK fusion gene." (PMID 31511040, 2019). "However, the frequency of EML4-ALK in the Western population is only around 1–7%, which means that more than 40% of non-small cell lung cancer (NSCLC) patients without EGFR or EML4-ALK mutations are left without any available targeted therapy." (PMID 22870311, 2012). "Use of this technique has also confirmed that, in non-small cell lung cancer, the fusion of ALK appears to occur solely with EML4, as previously reported, rather than with other genes." (PMID 20624322, 2010).
lung adenocarcinoma (152 papers, 2010 to 2026). A carcinoma that arises from the lung and is characterized by the presence of malignant glandular epithelial cells. "ALK rearrangements occur in approximately 3–10% of NSCLC patients, and echinoderm microtubule-associated protein-like 4 (EML4) is the most common ALK fusion partner in lung adenocarcinoma." (PMID 40052122, 2025). "This case demonstrates the potential for ensartinib in the treatment of EML4-ALK+ lung adenocarcinoma with multiple gene mutations." (PMID 40052122, 2025). "Overall, ensartinib showed potential in the treatment of EML4-ALK+ lung adenocarcinoma with multiple gene mutations." (PMID 40052122, 2025). "The EML4/ALK fusion gene has been extensively studied in lung adenocarcinoma and squamous cell carcinoma and is associated with metastasis." (PMID 40486961, 2025). "The present manuscript reports on an acquired ALK resistance mutation in an EML4/ALK-rearranged non–small cell adenocarcinoma of the lung." (PMID 38960389, 2025). "This case provides a reference for managing EML4-ALK+ lung adenocarcinoma with multiple gene mutations." (PMID 40052122, 2025). "This article retrospectively analyzes a case of advanced lung adenocarcinoma with the echinoderm microtubule associated protein like 4 (EML4)-ALK fusion variant 3 (V3)." (PMID 39962851, 2024). "The echinoderm microtubule-associated protein-like 4 (EML4)–anaplastic lymphoma kinase (ALK) fusion is a common genetic alteration estimated to exist in ∼5% of lung adenocarcinomas." (PMID 38458397, 2024). "Despite multiple misdiagnoses, rEBUS–TBCB successfully confirmed the presence of lung adenocarcinoma and identified an echinoderm microtubule-associated protein-like 4-anaplastic lymphoma kinase (EML4-ALK) E13:A20 gene rearrangement." (PMID 38306516, 2024). "Among ALK fusion mutations that occur in NSCLC, EML4 is the most common gene fusion partner in ALK-rearranged lung adenocarcinoma." (PMID 39911820, 2024). "Taken together, these results support the deregulation of arginine synthesis after HSP90 inhibition as a key mechanism with the potential to block cell proliferation in lung adenocarcinoma with mutated EGFR or EML4-ALK translocation." (PMID 37762133, 2023). "Our study is the first to focus on long-course neoadjuvant alectinib in lung adenocarcinoma with the EML4-ALK variant." (PMID 37409244, 2023). "In this report, we present for the first time an unreported case of lung adenocarcinoma with double ALK fusions of echinoderm microtubule-associated protein like 4 (EML4) and histone methyltransferase (SETD2), which is sensitive to alectinib." (PMID 37055606, 2023). "Here, we reported a patient with lung adenocarcinoma who was identified with EML4-ALK mutations when he progressed on an immune checkpoint inhibitor." (PMID 37007089, 2023). "Here, we present a patient with locally advanced lung adenocarcinoma associated with EML4-ALK fusion mutation, who received neoadjuvant chemotherapy and alectinib treatment, and then underwent thoracoscopic left lower lung lobectomy." (PMID 37663243, 2023). "Since the first discovery of echinoderm microtubule associated protein-like 4 (EML4)-ALK fusion in patients with lung adenocarcinoma in 2007, a variety of ALK fusion partners have been detected." (PMID 36172736, 2022). "We report a case of lung adenocarcinoma harboring a complex EML4-ALK (E13, A5, A20) fusion that coexisted with a BRAF mutation, as tested by DNA-NGS prior to treatment." (PMID 36221356, 2022). "Herein, we present a case of PD-L1-overexpressing lung adenocarcinoma that harbors both EML4-ALK gene rearrangement and BRAF mutation." (PMID 34804000, 2021).